IL1B (interleukin 1 beta)
Diseases named in the same sentence as IL1B in open-access papers (continued):
Sharing a sentence is not in itself a finding about the gene and the disease.
acne (continued). "In the interaction between TLR2 and P. acnes, NF-κB acts as an essential TLR2 downstream signal that has a major impact on inflammatory responses in acne by releasing various pro-inflammatory cytokines such as COX-2, iNOS, IL-1β, and TNF-α." (PMID 35269651, 2022). "The present study is the first to evaluate the serum levels of IL-1α, IL-1β, IL-6, IL-8, IL-12β, IL-15, TNF-α, and granulocyte-macrophage colony-stimulating factor in acne subjects compared with the levels in healthy controls." (PMID 31951642, 2020). "In clinical acne samples, P. acnes triggers activation of TLR-2 which modulates production of inflammatory cytokines, including TNF-α, IL-1β, IL-6, and IL-87,30." (PMID 29507345, 2018). "The bacterium can also induce the expression of IL-17 from peripheral blood mononuclear cells and promote Th17 and Th1 response pathways; activation of the Th17 axis and Th17 cytokines (IL-17, IL-1β, IL-6, and TGF-β) appears to play a pivotal role in acne." (PMID 30155445, 2018). "The proinflammatory cytokines IL-1β, IL-6, TNF-α and the chemokine IL-8 were all expressed at a higher level in acne lesions in the Finnish cohort." (PMID 25153527, 2014). "Inflammatory acne was regulated by inflammatory factors including TNF-α and IL-1β, which are secreted by monocytes." (PMID 24013774, 2013). "Recent studies have also revealed potential in acne treatment, with Photodithazine® combined with micro-LED technology effectively reducing acne lesions and key inflammatory biomarkers such as interleukin-1α, IL-1β, tumor necrosis factor-α, and IL-8." (PMID 40869370, 2025). "Indeed, the inflammatory milieu in sebocytes, as evidenced by increased levels of cytokines, including IL-6, IL-8, and IL-1β, and the lipid metabolism enzyme COX-2, is reportedly elevated in acne." (PMID 39944487, 2025). "For instance, S100A15-L exhibits a more pronounced response to pro-inflammatory Th1 cytokines, such as TNF-α, IFN-γ, and IL-1β, than S100A15-S, which may explain its ~25 times greater expression than S100A150-S in acne lesions, as suggested for psoriasis." (PMID 39744637, 2024). "In contrast, no significant anti-acne potential (IL-1β inhibition rate < 50%) was detected for the second most abundant flavonoid in the extracts and its glycoside, namely baicalein and baicalin." (PMID 38792254, 2024). "A total of 37 potential targets were predicted by network pharmacology, among which TNF, IL-1B, IL-6, ESR1, PPARG, NFκB1, STAT3, and TLR4 may be the key targets of GA in the treatment of acne." (PMID 38792208, 2024). "The inflammatory factors IL-1β and TNF-α have a close relationship with the pathogenesis of acne." (PMID 37894244, 2023). "Besides, isoglycyrrhizin inhibits inflammatory cytokines like IL-6, IL-8, TNF-α and IL-1β in NF-κB, p38 and ERK pathways in multi cells, all of which have been reported to be closely related to acne." (PMID 35211023, 2022). "As shown in the cytokine levels in serum of IL-6, IL-8, TNF-α and IL-1β, the CPT could inhibit the release of these cytokines, thus improving inflammation in acne rats." (PMID 34539397, 2021). "IL-17 is reduced by vitamins A and D. IL-1β and TNF-α are involved in acne inflammation." (PMID 32765835, 2020). "Decreased MMP-2 activity may lead to the production of cytokines such as IL-1β, Pro-IL-1β, TGF-β, latent TNF-α, and elevated triglycerides, which are the key modulators in acne." (PMID 31032338, 2019). "Moreover, nuclear factor (NF)-κB, activator protein (AP)-1, pro-inflammatory cytokines (TNF-α, IL-1β, IL-6, and IL-8), and metalloproteinases (MMP) are activated via upregulation of TLR-2 in facial acne lesions of patients." (PMID 29507345, 2018). "Moreover, the increased expression of cytokines and other inflammatory markers such as IL-1α, beta-defensins 1 and 2, TNF-α, IL-1β, IL-8, IL-10, matrix metalloproteinases MMP-1, MMP-3, MMP-9, CXCL-2 was found in acne lesions in vivo." (PMID 25153527, 2014).
acne (continued). "Therefore, in order to understand the expression of inflammation in the acne model, we selected the pro-inflammatory cytokine IL-1β, MMP-2, and the anti-inflammatory cytokine IL-10 as the detection indicators in this experiment to observe their expression levels in the acne inflammation model." (PMID 40520168, 2025). "Similarly, bio-fermented postbiotics derived from Lactobacillus and Bifidobacterium strains modulate the skin microbiome and significantly reduce pro-inflammatory cytokines (e.g., IL-1β, TNF-α), enhancing barrier function and reducing acne lesions by ≥30% in recent trials." (PMID 41463630, 2025). "Moreover, IGF-1 can promote the proliferation and differentiation of sebocytes and IL-1β production, increase sebum through sterol regulatory element-binding protein (SREBP) and interact with androgens to promote the development of acne." (PMID 38585341, 2024). "Indeed, in human keratinocytes, its expression is stimulated by cytokines typical for the acne inflammatory milieu, such as TNF-α, IFN-γ, and IL-1β, indicating that inflamed skin may trigger its production in the epidermis." (PMID 39744637, 2024). "Moreover, the prominent induction of genes, such as PTGS2, CXCL8, IL6, IL1B, matrix metalloproteinase 1 (MMP1) and NLRP3, even raised the possibility that EGF and PA may be involved in the pathogenesis of acne." (PMID 34025636, 2021). "More interestingly, data on the potential role of CAMP factor 2 as an inflammatory molecule in human skin has come from a recent study using ex vivo skin explants, which demonstrated higher levels of the CAMP protein, as well as IL-8 and IL-1β, in samples from acne patients versus non-lesional skin." (PMID 31086023, 2019). "MMP-2 is now recognized to cleave a large number of non-matrix substrates, including IGFBPs, IL-1β, pro-IL-1β, latent TGF-β, and latent TNF-α, which are the main factors in acne inflammation." (PMID 31032338, 2019).
disc degeneration (91 papers, 2009 to 2025). "The IL-1β is a pro-inflammatory cytokine closely linked to the pathogenesis of disc degeneration, showing increased production with its severity." (PMID 33921398, 2021). "Interleukin-1β (IL-1β) is the best studied pro-inflammatory cytokines implicated in disc degeneration." (PMID 33391467, 2021). "IL‐1β is an important inflammatory cytokine that has been reported to be closely linked to disc degeneration." (PMID 33111436, 2021). "IL1α, IL1β and IL1Ra and their composite genotype have previously been linked to disc degeneration and low back pain in the general population." (PMID 25207923, 2014). "In this study, we specifically targeted IL-1β because this cytokine has been implicated as a primary mediator of matrix catabolism in disc degeneration." (PMID 22863285, 2012). "rs1143633 in IL1B was associated with improvement of pain after surgery in our study while this SNP was found to be associated previously with the higher occurrence of disc degeneration (HIZ) what can be a potential chronic pain source." (PMID 35964023, 2022). "In addition, we have demonstrated that the antioxidant NAC treatment can delay the disc degeneration caused by Bmi‐1 deficiency or IL‐1β and TNF‐α stimuli." (PMID 32583517, 2020). "The NLRP3/caspase-1/IL-1β axis has been found to be active in human lumbar cartilaginous endplate degeneration and their expression levels are positively associated with the grades of disc degeneration." (PMID 31383789, 2019). "Furthermore, IL-1 receptor antagonist-deficient mice exhibit spontaneous disc degeneration, which, together with the increased risk of low back pain in patients with IL-1β polymorphisms, suggests a major role for IL-1β in the pathogenesis of disc degeneration." (PMID 28646230, 2017). "Based on previous observations that IL-1β elevated in degenerated discs 10 and IL-1β was mainly secreted through the secretory autophagy pathway in other pathogenic processes 14, 16, we examined whether secretory autophagy was involved in disc degeneration." (PMID 33391467, 2021). "The results of these studies suggest that Panax notoginseng might be useful for inhibiting the production of TNF-α, MMP-13, IL-1β and NO, which are associated with disc degeneration, and these effects could have caused the positive changes in disc height observed in this study." (PMID 23419188, 2013). "Inflammation is a critical driver of disc degeneration, characterized by elevated levels of pro-inflammatory cytokines such as IL-1β, TNFα, and IL-6, which exacerbate ECM degradation through the upregulation of matrix-degrading enzymes (MMPs, aggrecanases)." (PMID 40305345, 2025). "Inflammatory cytokines such as TNF-α, IL-1β, and IL-6 are known to promote disc degeneration by enhancing matrix degradation and inflammatory responses." (PMID 40467648, 2025). "The pro-inflammatory cytokine interleukin-1β (IL-1β) has been regarded as a principal factor in orchestrating disc degeneration." (PMID 40305345, 2025). "TNF-α and IL-1β are involved in initiation and progression of disc degeneration by regulating the inflammatory response, senescence, apoptosis, and matrix destruction." (PMID 40244065, 2025). "TNF-α and IL-1β contribute to disc cell aging, extracellular matrix degradation, and disc degeneration." (PMID 40244065, 2025). "IL-1β (10 ng/ml) was used to establish a humanized IDD model in human lumbar nucleus pulposus (NP) tissues from 36 patients with degenerative disc disease." (PMID 39906617, 2025). "This specificity is an important finding, as it suggests that the effects of LN are selective for IL-1β, known as a key mediator in disc degeneration pathogenesis." (PMID 40305345, 2025). "At the molecular level, the inflammatory cytokine interleukin-1β (IL-1β) plays a central role in mediating disc degeneration." (PMID 40305345, 2025). "Inflammatory cytokines, especially TNF-α and IL-1β, are known as key mediators in the progression of disc degeneration." (PMID 40244065, 2025).
disc degeneration (continued). "Quercetin was reported to prevent IL-1β-induced CS as well as to ameliorate disc degeneration in a puncture-induced rat model through inhibition of the NF-κB pathway and activation of the antioxidant Nrf2." (PMID 37189433, 2023). "In summary, this study elucidated the molecular mechanisms through which SRR inhibits IL-1β-mediated disc degeneration by modulating the TGF-β1/NF-κB pathway, using in vitro and in vivo models." (PMID 37928874, 2023). "Subsequent qPCR analyses demonstrated that the mRNA levels of IL-1β and p65 increased with the progression of disc degeneration, while the mRNA levels of TGF-β1 decreased accordingly." (PMID 37928874, 2023). "TNF-α and IL-1β levels have been positively correlated with the degree of severity of disc degeneration." (PMID 37206531, 2023). "It has been proved that IL-1β has important roles in the pathogenesis of disc degeneration by stimulating the apoptosis in disc cells." (PMID 35795857, 2022). "As mechanotransduction and signaling pathways can be altered in degeneration, calcium signaling was also investigated in the presence of IL‐1β (IL‐1) supplementation, a cytokine that has been shown to be an important component of disc degeneration." (PMID 36601377, 2022). "As a major pro-inflammatory factor, IL-1β recruited immune cells such as macrophages and neutrophils to the site of inflammation, releasing inflammatory mediators and exacerbating disc degeneration." (PMID 35935259, 2022). "Inflammatory processes exacerbated by TNF‐α and/or IL1β are believed to trigger disc degeneration and, in later stages, low back pain." (PMID 35106811, 2022). "Caudal IVD segments were evaluated for disc degeneration by histopathology, functional testing, and inflammatory gene expression relevant to IL‐1β pathways." (PMID 35783913, 2022). "Both ELISA and qRT-PCR analysis showed that the expression levels of inflammatory cytokines TNF-α, IL-1β, IL-6, and IL-17 were inhibited after overexpressing c-Jun in the disc degeneration rats." (PMID 34308759, 2021). "Inflammatory processes exacerbated by several cytokines (i.e., TNF-α and IL-1β) are key mediators of disc degeneration and the resultant low back pain." (PMID 34616848, 2021). "Previously, several studies have showed that inflammatory cytokine IL-1β facilitates disc AF cell apoptosis whereas inhibition of IL-1β has been shown to suppress disc cell apoptosis and inhibit disc degeneration." (PMID 34616848, 2021). "Compared with NPCs from patients with grade IV disc degeneration, the expression of cleaved CASP1, IL-1β and IL-18 was higher in NPCs from patients with grade V disc degeneration." (PMID 32320383, 2020). "First, we activated the p38 MAPK pathway using the inflammatory factor IL-1β at the excessive concentration of 10 ng/mL to induce disc degeneration." (PMID 32023553, 2020). "Using these discs, an in vitro disc degeneration model was developed by the intervention of IL‐1β and TNF‐α as described." (PMID 32583517, 2020). "During the process of disc degeneration, IL-1β is upregulated, while IL-1Ra levels decrease, leading to hyperactive IL-1β signaling and accelerating the progression of IDD27." (PMID 31554783, 2019). "Our present results showed that the expression of TNF-α, IL-1β and cleaved caspase 3 in degenerative disc disease (DDD) tissues are higher than those in lumbar vertebral fracture (LVF) tissues." (PMID 31518335, 2019). "In conclusion, the selective c-Fos/AP-1 inhibitor T-5224 prevented disc degeneration in an explant culture model of mouse IVD induced by IL-1β and in a rat model of IVD degeneration induced by needle puncture." (PMID 29208967, 2017). "Intervertebral discs are known to respond to IL1A and IL1B in the multiple pathological processes of disc degeneration, such as inhibiting synthesis of the extracellular matrix and increasing synthesis of matrix metalloproteinases." (PMID 27253397, 2016).
disc degeneration (continued). "IL-1β has been shown to be upregulated in NP cells during disc degeneration in vivo and upregulated in response to LPS or TNF-α treatment in vitro." (PMID 24936787, 2014). "In contrast, induction of disc degeneration using IL-1β and TNF-α mimics the pathways that drive inflammatory processes and disease phenotype in humans." (PMID 24171898, 2013). "A recent study even specified that the biochemical mediators of inflammation and tissue degradation including MMP-3, IL-1β and inducible nitric oxide synthase were significantly increased along with the disc degeneration that was induced by needle puncture." (PMID 19912653, 2009). "TNFα and IL1β are the two inflammatory cytokines often used to recreate an inflammatory microenvironment in some in vitro models of tissue degeneration, including OA and disc degeneration." (PMID 37958603, 2023). "In a porcine model, lumbar discs treated with exogenous TNF-α displayed degenerative alterations, including annular fissures, loss of NP matrix, vascularization, and expression of IL-1β in the outer annulus, indicating that TNF-α is a driver of disc degeneration." (PMID 37101594, 2023). "The researchers reported that resveratrol could partly suppress IL-1β-induced NP cell apoptosis, attenuating inflammation-response-induced disc degeneration." (PMID 35742903, 2022). "On the other hand, extracellular matrix catabolic products produced during disc degeneration may promote macrophage-mediated IL-1β and tumor necrosis factor α (TNF-α) production through activation of NF-κB/IκBα complexes." (PMID 35333664, 2022). "IL1B is involved in multiple pathological process of disc degeneration." (PMID 35964023, 2022). "In the present study, we demonstrate for the first time that IL-1β released through secretory autophagy contributes to disc degeneration in both human and animal models and that pharmacologic inhibition of this pathway can ameliorate age-related and injury-induced disc degeneration in rodents." (PMID 33391467, 2021). "Given the important contribution of IL-1β to disc degeneration in patients, IL-1β-related pathways may be promising therapeutic targets for clinical intervention." (PMID 33391467, 2021). "In our study, induction of IL-1β through secretory autophagy and more co-localization of secretory autophagy markers (TRIM16 and LC3B) in degenerated discs pointed that secretory autophagy may contribute to disc degeneration with IL-1β secretion." (PMID 33391467, 2021). "Moreover, the expression of TNF-α and IL-1β increases with aging and degree of disc degeneration in degenerative human discs and animal discs." (PMID 34616848, 2021). "Furthermore, they showed differences in overexpression of selective inflammatory and catabolic proteins (p<0.0001) similar to those found in human NP cells of different disc degeneration grades, such as IL-1β, TNF-α, ADAMTS-4, ADAMTS-5 and MMP-3." (PMID 31751427, 2019). "Similarly, in degenerative disc disease (DDD) there is compelling evidence for the fundamental roles of IL-1β in its pathology." (PMID 30155445, 2018). "Even though both IL-1β and TNF-α could be implicated in the pathogenesis of disc degeneration, IL-1β could be a better therapeutic target for IVD regeneration." (PMID 24278441, 2013). "Attenuating the catabolic effects of IL-1β in the NP may be an essential therapeutic step in slowing or reversing disc degeneration." (PMID 22863285, 2012). "Our findings demonstrate that LN directly interacts with IL-1β, effectively inhibiting its signalling and modulating its downstream effects in NP cells and DRG neurons, offering a potential therapeutic strategy for mitigating inflammation-associated disc degeneration." (PMID 40305345, 2025). "Additionally, IL-1β induces oxidative stress and activates caspase signaling pathways, leading to the apoptosis of nucleus pulposus cells (NPCs) and annulus fibrosus cells (AFCs), further exacerbating disc degeneration." (PMID 40688090, 2025).